MRPS18C (mitochondrial ribosomal protein S18C)
Synonyms: MRP-S18-1; MRP-S18-c; Mrps18-c; S18mt-c; CGI-134; MRPS18-1; FLJ11146; FLJ22967; bS18m
Tractability: Small molecule: a structure with a bound ligand is known. PROTAC: ubiquitination databases record sites on it; its protein half-life has been measured.
Gene: Protein-coding gene on chromosome 4 (83,455,932 to 83,470,428, forward strand). Ensembl gene ENSG00000163319.
Subcellular location: Mitochondrion
Pathways (Reactome):
Metabolism of proteins: Mitochondrial ribosome-associated quality control; Mitochondrial translation elongation; Mitochondrial translation initiation; Mitochondrial translation termination
Gene Ontology:
Molecular function: small ribosomal subunit rRNA binding; structural constituent of ribosome
Biological process: mitochondrial translation; translation
Cellular component: mitochondrial small ribosomal subunit; mitochondrion; mitochondrial inner membrane; ribosome
Genetic constraint (gnomAD): Loss-of-function variants: 16 observed, 13.78 expected, observed/expected ratio (o/e) 1.16, 90% interval 0.78 to 1.72. The upper end of that interval is the gene's LOEUF score, 1.72, which puts it in group 6 of 6, group 1 being the genes least tolerant of losing a copy. Missense variants: 98 observed, 116.49 expected, observed/expected ratio (o/e) 0.84, 90% interval 0.71 to 1. Synonymous variants: 50 observed, 39.72 expected, observed/expected ratio (o/e) 1.26, 90% interval 1 to 1.59.
Homologues: Orthologues: chimpanzee MRPS18C (100% identical), macaque MRPS18C (95% identical), dog MRPS18C (85% identical), pig MRPS18C (85% identical), guinea pig MRPS18C (84% identical), mouse Mrps18c (80% identical).
Diseases named in the same sentence as MRPS18C in open-access papers:
MRPS18C is named in the same sentence as 6 diseases in open-access papers, as found by Europe PMC text mining. Sharing a sentence is not in itself a finding about the gene and the disease. The quoted sentences say what the papers report.
breast carcinoma (1 paper, 2016). "MRPS18C is part of the small subunit (28S) of the mitochondrial ribosome involved in oxidative phosphorylation and thus the role of this protein in breast cancer susceptibility is unclear." (PMID 27792995, 2016).
schizophrenia (1 paper, 2018). A major psychotic disorder characterized by abnormalities in the perception or expression of reality. "Additionally, the intra-module hub gene from a yellow module with the highest value of connectivity was a schizophrenia-associated gene known as HINT1, and two of the top five connected intra-module hubs in module yellow were MRPS18C and NDUFA12, which are implicated in the function of mitochondria." (PMID 29958387, 2018).
MRPS18C also shares sentences with these, for which no sentence is quoted: hypothyroidism (1 paper); myocardial ischemia (1); Sepsis (1); tumor (1).